STAT3 (signal transducer and activator of transcription 3)
Diseases named in the same sentence as STAT3 in open-access papers (continued):
Sharing a sentence is not in itself a finding about the gene and the disease.
tumor (continued). "We found that down-regulation of STAT3 by miR-124 leads to increased cancer cell death and reduced tumor load when transplanted in mice." (PMID 23940556, 2013). "Signal transducer and activator of transcription-3 (STAT3) is critical for cancer progression by regulating tumor cell survival, proliferation, and angiogenesis." (PMID 24324713, 2013). "The VEGF/VEGFR2-mediated STAT3 signaling pathway is a potential key target of anti-angiogenic tumor therapy." (PMID 23731702, 2013). "Epidermal-specific knockout of Stat3 in the K14.SmoM2 transgenic mice significantly reduced SmoM2-mediated epidermal hyperplasia and tumor development." (PMID 23577258, 2013). "Western blot analysis of tumor-associated B cells and B cells from the tumor-draining lymph nodes also confirmed an important role of Stat3 intrinsic to B cells in promoting expression of angiogenic factors in the tumor microenvironment." (PMID 23734190, 2013). "Activation of STAT3 appears to shift immune response toward cancer’s advantage, thus, its inhibition is attractive for possible improvement of anti-tumor immune responses." (PMID 23755373, 2013). "STAT3 signaling triggers crosstalk between tumor cells and TAMs, and is crucial for the regulation of malignant progression." (PMID 23825527, 2013). "Inhibition of STAT3 activity enhances chemosensitivity of multiple tumor types to a number of different cytotoxic agents or other targeted agents." (PMID 23531921, 2013). "STAT3 has been shown to have a central role in several aspects of tumor aggressiveness, including proliferation, invasion, and migration." (PMID 23351302, 2013). "It has been reported that IL-6 is a major activator of STAT3 signaling, and the activation of STAT3 signaling plays a role in the induction of aggressive tumor behavior and EMT changes in cancer." (PMID 23637926, 2013). "In cancer cell lines and in patient tumor tissues, there is evidence for constitutive activation of STAT3 through chronic cytokine stimulation through autocrine and/or paracrine loops, often involving IL-6." (PMID 24324713, 2013). "STAT3 now has been considered as one of the critical oncoproteins mediating regulation of cell invasion and tumor microenvironment." (PMID 23704931, 2013). "Among the Tumor-promoting activities ascribed to persistent STAT3 signaling are those involved with cell proliferation, metastasis, angiogenesis, host immune evasion, and resistance to apoptosis." (PMID 23382914, 2013). "Taken together, our studies show that B cells are an important source of angiogenic factors and B cell intrinsic Stat3 activity is crucial for B cell production of pro-angiogenic factors in the tumor milieu." (PMID 23734190, 2013). "MiR-124 therefore serves as a tumor suppressor through inhibition of STAT3 signaling, which explains its down-regulation in human CRC and other cancers." (PMID 23940556, 2013). "A particular member, STAT3, has been shown to be constitutively active in a number of human tumor cell lines as well as primary tumors, including haematological malignancies." (PMID 23738079, 2013). "Persistently activated Stat3 and Stat5 molecules and Stat induced target gene expression can be found in tumor cells." (PMID 24276378, 2013). "We found that STAT3 likely up-regulates a number of oncogenic pathways to promote aggressive tumor growth and migration." (PMID 24142927, 2013). "We have previously demonstrated that phosphorylated signal transducer and activator of transcription-3 (pSTAT3) plays a critical role in cancer-related inflammation and tumor progression through recruitment of myeloid cells and Tregs." (PMID 23326565, 2013). "Genetic or pharmacological inhibition of STAT3 abrogated Akt activation and combined gefitinib with STAT3 inhibition synergistically reduced the growth of the tumor cells." (PMID 24280348, 2013).
tumor (continued). "Previously, we have demonstrated that blocking STAT3 signaling in the APCs by specific inhibitors resulted in reduced IL-10 expression and reversal of hMSC and tumor cell-mediated inhibition of proinflammatory cytokines." (PMID 24073274, 2013). "Mechanically, we found AKT/mTOR, ERK, as well as JAK2/STAT3 pathways account for the anti-tumor effects of simvastatin." (PMID 23690956, 2013). "Previously, NF-κB activation in human cancers has been reported to be positively or negatively correlated with STAT3 activation in the control of tumorigenesis, tumor growth and angiogenesis." (PMID 23402362, 2013). "In conclusion, our data indicate that resveratrol has potent anti-tumour effects against malignant NK cells that are mediated through inhibition of constitutively active STAT3 signals due to blocking JAK2 kinase." (PMID 23372833, 2013). "The decrease in Fak and Stat3 activity in J110 tumours treated with the Ret inhibitor was studied in more detail in the cell lines." (PMID 23868506, 2013). "IL-6, a multi-functional cytokine, is the main activator of STAT3 signaling and the inducer for androgen receptor (AR) expression, STAT3 activation has been reported to mediate the radioresistance of tumor, and be up regulated by IL-6." (PMID 23806095, 2013). "A crucial role for tumor STAT3 in upregulating proliferation/survival of tumor cells as well as dampening proper function of immune cells such as myeloid cells and T cells has been well characterized." (PMID 23734190, 2013). "In our investigation we evaluated the correlation between miR-155, SOCS1 and STAT3 in 63 tumor and 21 control mucosa specimens." (PMID 23437123, 2013). "In contrast, activated signal transducer and activator of transcription 3 (STAT3) is a protein that promotes tumor cell survival by inhibiting apoptosis and has an important role in cancer progression in many of cancer types." (PMID 24098947, 2013). "Activated STAT3 has been shown to protect tumor cells from apoptosis by inducing proliferation/survival genes and blunting pro-apoptotic genes." (PMID 24324713, 2013). "In this study we demonstrated that excessive IL-22 in the CC and UC microenvironment leads to tumor growth, inhibition of apoptosis, and promotion of metastasis depend on STAT3 activation." (PMID 23379788, 2013). "Intestinal inflammation and tumor development were assessed by endoscopy and histology, gene expression by real-time PCR, Stat3 phosphorylation by immunoblot, cytokines by ELISA and apoptosis by TUNEL assay." (PMID 24223168, 2013). "Putative tumour initiating cells previously have been shown to express the embryonic stem cell-specific genes Oct4, Nanog and STAT3, which are important for self-renewal, proliferation, and fate determining properties of stem cells." (PMID 23219486, 2013). "In this model, the SMAD2/3 and STAT3 signaling pathways are activated in tumor cells as shown using CHLA-255 SMAD2/3 and STAT3 Fluc reporter cell lines, and activation is inhibited by lenalidomide." (PMID 23982484, 2013). "Treatment of Stat3 inhibitor WP1066 in B16-F10 tumor cells inoculated wild-type mice inhibits tumor growth." (PMID 24453427, 2013). "Interleukin-6 (IL-6) mediated Stat3 activation is viewed as crucial for multiple tumor growth and progression." (PMID 24191246, 2013). "To evaluate the effect of AZD1480 on STAT3 activation in vivo, we collected tumor samples from mice after 9-doses of AZD1480 or vehicle." (PMID 23531921, 2013). "STAT3 activation increased NF-κB activation and tumor growth derived from cervical cancer cells or glioblastoma cells." (PMID 23402362, 2013).
tumor (continued). "Previous paper indicated that IL-17 expression positively correlated with Stat3 activity in growing tumor." (PMID 24453427, 2013). "It is observed that tumor cells having constitutively active STAT3 signalling recruit immune cells and subvert their function for self-benefit." (PMID 24199193, 2013). "In our study, legumain-targeting liposomal nanoparticles (NPs) encapsulating HC were employed to suppress STAT3 activity and “re-educate” TAMs, and to investigate the effects of suppression of tumor progression in vivo." (PMID 23825527, 2013). "Herein we provide evidence of the anti-tumor effect of blocking JAK2/STAT3 pathway by using the JAK2 inhibitor AZD1480 in 3 different types of pediatric solid tumor models." (PMID 23531921, 2013). "JAK/STAT3 signaling is deregulated in majority of human cancers and promotes tumor growth and metastasis." (PMID 24199193, 2013). "Recent evidence has demonstrated that aberrant Stat3 signaling by Interlukin-6 (IL-6) in cancer cells is a major mechanism for tumor initiation, development, progression, and metastasis." (PMID 24191246, 2013). "STAT3 is found aberrantly activated, downstream of IL-6, in a number of chronic inflammatory conditions leading to tumour transformation or auto-immunity." (PMID 23460527, 2013). "In this study, we demonstrate the suppressive effect of tumor growth by berberine through inhibiting STAT3 activation." (PMID 24380387, 2013). "Tsai and colleagues demonstrated that secretion of IL-6 by MSCs activated the signal transducer and activator of transcription-3 pathway in cancer cells and promoted tumor formation." (PMID 23763837, 2013). "Tumor-derived IL-6 drives STAT3 nuclear translocation in immature myeloid cells, thus promoting proliferation and inhibiting apoptosis of MDSCs." (PMID 24339824, 2013). "Several reports show that signal transducer and activator of transcription 3 (STAT3) is crucial for tumor angiogenesis." (PMID 23734190, 2013). "Soluble tumor-cell-derived factors trigger mononuclear cells to co-secrete lineage-specific EGFR agonists together with a common STAT3 activator." (PMID 23597096, 2013). "Recently, phosphorylated-Stat3 expression in the tumor stroma, an indication of IL-6-JAK pathway activation, was thought to be a critical contributor to cancer progression and response to therapy by modulating PI3K pathway." (PMID 23922669, 2013). "Not only important for promoting tumor growth, Stat3+/+ B cells also accelerate tumor progression through upregulating metastatic potential of B16 tumor cells in vivo." (PMID 23734190, 2013). "Inhibition of mitochondrial STAT3 by P-V was required for its anticancer effect; mitochondrial STAT3 overexpression rescued animals from the tumor growth inhibition by P-V." (PMID 23650499, 2013). "In summary we provide the first pre-clinical proof of concept of the anti-tumor potency of inhibition of JAK/STAT3 pathway in pediatric solid tumors utilizing AZD1480." (PMID 23531921, 2013). "Simultaneously, up-regulation of tyrosine phosphorylation of STAT3 (p-STAT3, Tyr705) was investigated in both macrophages and tumor cells in a manner of time-dependence." (PMID 23825527, 2013). "Matrigel plugs containing both tumor cells and Stat3+/+ B cells exhibited markedly increased tumor vascularization in vivo, compared to those with only B16 tumor cells or B cells." (PMID 23734190, 2013). "An inhibitor of JAKs, upstream molecules of STAT3, was reported to augment anti-tumor effects in combination with immunotherapies such as IL-12 administration." (PMID 23755373, 2013). "We also revealed that cancer cells affect IL-6 production from stromal fibroblasts through IL-1 signaling and that IL-6 is important for tumor growth through STAT3 activation." (PMID 23593346, 2013). "All these results support a novel role of berberine to inhibit STAT3 signaling in NPC by targeting fibroblasts present in tumor stroma." (PMID 24380387, 2013).
tumor (continued). "Western blot was used to detect STAT3 protein expression in 63 tumor and 21 control mucosa specimens." (PMID 23437123, 2013). "A predominance of STAT3 and STAT6 activation results in M2 macrophage polarization, associated with immune suppression and tumor progression." (PMID 24574581, 2013). "Regardless of which upstream signaling molecules are deregulated, the tumor-promoting effects of persistent activation of these signaling pathways are ultimately mediated by STAT3-dependent transcriptional regulation of downstream proto-oncogenes." (PMID 24260381, 2013). "In this model of skin carcinogenesis, Stat3 is activated very early in the epidermis following treatment with different classes of tumor promoters, including TPA, okadaic acid, and chrysarobin." (PMID 23577258, 2013). "STAT3 protein expression was also compared between 21 pairwised tumor and control mucosa specimens obtained from 21 patients who received total laryngectomy." (PMID 23437123, 2013). "Here, we used fibroblasts isolated from primary human NPC tumor biopsy to develop an in vitro system to mimic the in vivo secretion of IL-6 by stromal cells and the subsequent activation of STAT3 in cancer cells." (PMID 24380387, 2013). "While some report suggest the oncogenic role of B1 regulatory cells in mouse tumor models, further studies are required to define the subset of B cells with persistently activated STAT3 in B cell-mediated tumor angiogenesis." (PMID 23734190, 2013). "Our study further reveals a previously unrecognized role of B cell STAT3 in accelerating tumor progression through increasing angiogenesis." (PMID 23734190, 2013). "We have shown that TF expression is regulated by Stat3, and therefore, the effects of Stat3 activation on TF activity and tumor formation were evaluated." (PMID 24086497, 2013). "Tumor growth and metastasis was promoted by STAT3 phosphorylation and upregulation of its downstream genes such as Bcl-xl, CyclinD1, and VEGF." (PMID 23379788, 2013). "The protein levels of STAT3 in tumor tissues were 1.8-fold higher than those in control mucosa tissues; the differences were statistically significant (p<0.001)." (PMID 23437123, 2013). "In many STAT3 constitutive activated cancer cells, either cultured human tumor cells or generated mouse models, blocking STAT3 signaling will inhibit cell growth, induce apoptosis and reduce cell metastasis." (PMID 23704931, 2013). "Ex vivo angiogenesis assays show that B cell-mediated tumor angiogenesis is mainly dependent on the induction of pro-angiogenic gene expression, which requires Stat3 signaling in B cells." (PMID 23734190, 2013). "Emerging evidence has demonstrated that hyperactivation of STAT3 contributes to carcinogenesis in a variety of cancer types and disruption of the STAT3 signaling decreased tumor growth." (PMID 24280348, 2013). "Our in vitro experiments provide evidence that, in ESFT cell lines, STAT3 plays its classical role of contributing to tumour growth and regulating the tumour immune environment." (PMID 22315522, 2012). "In this study, we demonstrated that the inhibitory role of PTPMeg2 on tumor growth was mainly through dephosphorylation of STAT3." (PMID 22394684, 2012). "This diversity of STAT3 functions in different tumor cellular contexts certainly warrants further investigation." (PMID 22723956, 2012). "Secondly, LLL12 reduced tumor-associated angiogenic factors (VEGF, MMP-9, angiopoetin, TF and FGF1), probably as a direct consequence of STAT3 inhibition in tumor cells." (PMID 22530037, 2012). "Several therapeutic strategies directing at STAT3 have been developed, which focus on the anti-tumor effect only." (PMID 23554768, 2012). "We were particularly interested in the role of STAT3 in contributing to tumour growth and immune regulation, which are classical roles described for STAT3 in adult tumours." (PMID 22315522, 2012).
tumor (continued). "The main finding of this study is the demonstration of a distinct phenotype of tumor cells (CA125+++EpCAM+++/STAT3+++), as well as stromal cells (CD44+++/Oct4+++) isolated from the ascites of a limited number of CR patients (n = 4)." (PMID 23056490, 2012). "We sought to confirm that STAT3 is present in a subset of ESFT tumours and to investigate the role of STAT3 in ESFT." (PMID 22315522, 2012). "This crosstalk is initiated by the release of IL-6, resulting from the NFκB-dependent activation of the IL-6 promoter, and the subsequent tyrosine phosphorylation of STAT3 by the autocrine/paracrine activation of IL-6 receptors in tumor cells." (PMID 22545054, 2012). "Blocking STAT3 protein in human tumor cells has been shown to down-regulate Mcl-1 expression and induce tumor cell apoptosis." (PMID 23166634, 2012). "Because its activation can mediate oncogenic transformation in cultured cells and tumor formation in nude mice, Stat3 has been classified as an oncogene." (PMID 22303479, 2012). "STAT3 was activated (tyrosine 705-phosphorylated) in 18 out of 31 primary tumours (58%), either diffusely (35%) or focally (23%)." (PMID 22315522, 2012). "All these results indicated that PTPMeg2 inhibits STAT3 phosphorylation directly and PTPMeg2 is a tumor suppressor." (PMID 22394684, 2012). "In tumour cell lines, STAT3 can induce VEGF production either directly via activation of VEGF transcription or indirectly viahypoxia-inducible factor 1α." (PMID 24977103, 2012). "Certainly the biologic characteristics of each tumor type likely influence their response to STAT3 inhibition." (PMID 22899991, 2012). "Because constitutively active STAT3 up-regulates anti-apoptotic genes to promote tumor survival, its inhibition by GRIM-19 demonstrates an anti-oncogenic effect exerted by biological therapeutics." (PMID 23061049, 2012). "Since STAT3 is involved in various aspects of cancer growth ranging from tumor initiation, angiogenesis, and metastasis, it represents an attractive target for intervention." (PMID 22280969, 2012). "Before elucidating the role of M-HIFU on STAT3 activation, we examined several tumor cell lines for STAT3 activity and found that a high level of p-STAT3 was expressed in RM-9 cells." (PMID 22911830, 2012). "A number of experimental strategies targeting the Jak2/STAT3 pathway have been shown to enhance the anti-tumor effects of immune-based therapies in pre-clinical tumor models." (PMID 22899991, 2012). "In this study, we proposed that MSM suppresses tumor growth via inhibition of the STAT3 and STAT5b pathways." (PMID 22485142, 2012). "Bcl-xL, also a major STAT3 target gene, is an anti-apoptotic molecule of the Bcl-2 family and enhances tumor progression." (PMID 22911830, 2012). "In consistence with the tumor growth experiment, we examined the expression of STAT3 downstream genes." (PMID 22394684, 2012). "Overall, our results suggest that M-HIFU can inhibit STAT3 activation, which leads to an anti-tumor response through two potential mechanisms." (PMID 22911830, 2012). "Our results show a significantly reduced expression (MFI) of pY705-Stat3 in the presence of ATC or aATC regardless of AT-101 sensitization, suggesting that ATC and aATC alone are potent inhibitors of Stat3 phosphorylation in the tumor cells." (PMID 23185240, 2012). "Since Stat1 and Stat3 are often expressed simultaneously in the same tumor cells, it has been suggested that one protein dominates over the other in the influence on survival, depending on e.g. the durability of activation of each protein." (PMID 22838736, 2012). "We therefore examined the effect of EEHDW on STAT3 phosphoralytion in tumor tissue by Western blot analysis using antibody that recognizes STAT3 phosphorylation at Tyr705." (PMID 22754353, 2012). "The STAT3 is also persistently activated in about half of NSCLC tumours and is involved in tumour invasion, metastasis and angiogenesis through differential gene regulation." (PMID 22333600, 2012).